PARP1 (poly(ADP-ribose) polymerase 1)
Diseases named in the same sentence as PARP1 in open-access papers (continued):
Sharing a sentence is not in itself a finding about the gene and the disease.
breast cancer (continued). "In the 4T1 breast cancer mouse model, suppression of KLF4 expression significantly sensitizes breast cancer tumors to olaparib, clearly demonstrating the clinical relevance of KLF4 in synergizing PARP1 in anti‐TNBC breast cancer treatment." (PMID 33231937, 2020). "Olaparib is an inhibitor of PARP1, PARP2, and PARP3 enzymes involved in DNA repair and is currently approved for the treatment of ovarian and breast cancers." (PMID 32117762, 2020). "Upon activation of its catalytic activity, PARP1 ADP-ribosylates the nucleolar RNA helicase DDX21, which results in enhanced rDNA transcription and proliferation of breast cancer cells." (PMID 32640701, 2020). "PARP1 knockdown and PJ34 mediated inhibition showed reduced CCL2 transcript levels in breast cancer cells, corroborating the findings from the sequencing data." (PMID 32455851, 2020). "Down-regulated expression levels of MCM2 (mini-chromosome maintenance complex component 2), PARP1, and BRCA1 (breast cancer type 1) genes in CBD-treated HNSCC were confirmed by quantitative real-time RT-PCR and then compared with the RNA-seq results." (PMID 33244087, 2020). "Incubation with PJ34 at higher concentrations than those inhibiting PARP1 (10–20 μM PJ34), completely eradicated within 48 h human MCF-7 breast cancer cells that are resistant to doxorubicin." (PMID 32575437, 2020). "PARylation of HMGA2 following alkylating DNA damage provided further evidence for a functional interaction between PARP1 and HMGA2 in fibrosarcoma and breast cancer cells." (PMID 30289618, 2019). "Beyond validating miR-222 overexpression in tamoxifen resistant cells, this is the first demonstration that upregulation of miR-222 increases PARP1 activation and PARPi sensitivity and decreases RAD51 foci formation in breast cancer cells." (PMID 30621214, 2019). "In breast cancer cells, NR1D1 is recruited to DNA damage sites and therein interacts with poly (ADP-ribose) polymerase 1 (PARP1) and subsequently inhibits the recruitment of the DNA damage response complex including SIRT6, pNBS1, and BRCA1." (PMID 31779659, 2019). "Western blotting of PARP1 co-immunoprecipitated proteins confirmed the direct interaction of PARP1 with ARID1A and BRG1, but also with other subunits of SWI/SNF, such as SMARCC1 and SMARCC2, in the studied breast cancer cell lines." (PMID 31614656, 2019). "We tested two predicted OCN pairs in each cancer type, including NCSTN and DNM1, and NCSTN and OGT in liver cancer; CCNA2 and PTP4A1, and HIF1A and PARP1 in lung cancer; and CCNA2 and PTP4A1, and PLK1 and PTP4A1 in breast cancer." (PMID 31097707, 2019). "It was revealed in a breast cancer model (MCF7, ERα-positive) that in response to estradiol, ERα and PARP1 co-localize to ERα-target genes to regulate their expression." (PMID 30621214, 2019). "To evaluate influence on PARP1 activity, we down-regulated the expression of RIT1, PSAT1 and INCENP by using siRNA and analyzed the level of PARylation in MCF7 breast cancer cell line." (PMID 31105872, 2019). "PARP-1 mediated PARylation of the lysine demethylase, KDM5B, inhibited binding to its target proteins and maintained the H3K4me3 methylation status in MCF7 breast cancer cells." (PMID 29541423, 2018). "Our work, which focused on breast cancer cells that are inherently resistant to PARP-1 inhibitors, showed that vorinostat sensitized them to the inhibition of PARP-1." (PMID 29938005, 2018). "Based on the roles of PARP1, γH2AX, BRCA1, and BRCA2 in DNA damage repair, the combined expression patterns were evaluated in breast carcinoma and soft tissue sarcomas." (PMID 29784019, 2018).
breast cancer (continued). "In this context, the combined expression patterns of DDR molecules expressed in single- and double-strand breaks of DNA such as PARP1, γH2AX, and BRCA1/2 were indicators of poor prognosis of breast carcinomas and soft-tissue sarcomas." (PMID 30126387, 2018). "Treatment of human breast cancer MDA-MB-231 and SK-BR-3 cells with 10 μM of proteasome inhibitor MG-132 resulted in an accumulation of endogenous PARP1 in a time-dependent manner, indicating that PARP1 undergoes proteasome-dependent degradation." (PMID 29212245, 2017). "MK-4827 Niraparib (Merck/Tesaro), used for oral administration, is a potent inhibitor of PARP1 and PARP2 and is currently being tested in Phase III clinical trials as maintenance therapy in ovarian cancer and as a treatment for breast cancer." (PMID 27884198, 2016). "HR defective cells, such as breast cancer cells harboring mutant BRCA1, display greater than normal sensitivity to poly ADP ribose polymerase 1 (PARP-1) inhibition." (PMID 27197561, 2016). "To determine the prevalence and clinical significance of PARP1, BRCA1 and BRCA2 in breast cancer development, we investigated their expression in 110 cases of tissues and adjacent normal tissues by using immunohistochemistry." (PMID 25865228, 2015). "When the cancer sera were tested against a combination of two antigens, higher frequency (P < 0.01) of autoantibodies against PARP1 and BRCA1 was found in breast cancer and ovarian cancer." (PMID 25865228, 2015). "We found PARP1 enriched at TSS of actively transcribed gene promoters in both MCF7 and MDA-MB231 breast cancer cell lines." (PMID 26305327, 2015). "The expression of both PARP1 and BRCA1, both PARP1 and BRCA2, or both BRCA1 and BRCA2 in breast cancer were 17%, 22%, and 15%, respectively." (PMID 25865228, 2015). "This was significantly higher autoantibody responses to PARP1 and BRCA1/BRCA2 (especially to PARP1 and BRCA1) in ovarian cancer and breast cancer compared to normal control sera (P < 0.001 and P < 0.01)." (PMID 25865228, 2015). "Lestaurtinib amplifies the ability of the PARP1 inhibitor AG14361 to kill BRCA1 mutant and wild-type breast cancer cells, at least in part, by inhibiting NF-κB signaling." (PMID 24962108, 2014). "In the case of miR-182, which has been described to be upregulated in breast carcinoma, to target specifically BRCA1 gene and to be involved in the resistance to PARP-1 inhibitors, we identified a relationship between miR-182 expression and clinical outcome." (PMID 25369070, 2014). "Additional studies have demonstrated that the Chk1 inhibitor AZD7762 synergistically combined with numerous PARP1 inhibitors (including olaparib, rucaparib or ABT888) to inhibit the growth of mammary carcinoma cells in vitro and in vivo." (PMID 25104095, 2014). "For example, some drug-resistant breast cancer cells are known to overexpress vault PARP (vPARP), the first cytoplasmic PARP discovered (PARP-1 has a nuclear localization)." (PMID 23254695, 2013). "Thus, PARP-1 may be an important target for BRCA-deficient breast cancer chemotherapy, as emphasized also by the clinical activity of the PARP inhibitor (PARPi) olaparib in patients with BRCA-mutated breast cancer." (PMID 24191908, 2013). "This compound displays potent PARP-1 and PARP-2 inhibition, and inhibits proliferation of breast cancer cells with mutant BRCA-1 and BRCA-2 with IC50 in the range of 10-100 nM." (PMID 21504625, 2011). "Two breast cancer cell lines (T47D, MDA-MB-231) and the bone marrow stromal cell line (HS-5) showed lower expression levels of PARP-1 compared with the other cell lines (<mean−s.d)." (PMID 19568233, 2009). "Their activity was evaluated by PARP1 inhibition, cardiolipin affinity, and cytotoxicity in BRCA1-deficient HCC1937 breast cancer cells and non-malignant H9C2 cardiomyocytes." (PMID 41594705, 2026).
breast cancer (continued). "Notably, HyT 3a effectively induced PARP1 degradation in BRCA-mutant breast cancer and TNBC cells, achieving approximately 60% PARP1 degradation in MDA-MB-231 cells at 2.5 μM over 48 h, exhibiting superior antitumor efficacy compared to olaparib." (PMID 41497405, 2026). "A correlation was also reported between PARP1 and BRCA1/2, and at the same time, with ERBB2 and PGR in the luminal B subgroup; such results can indicate that those breast cancer patients can receive Anti-HER2 Monoclonal Antibodies and anti-PGR drugs available in the clinic at present." (PMID 40141415, 2025). "Such analysis by bioinformatics showed that there was a correlation between PARP1 and BRCA1/2, and at the same time, with ESR1 in the HER2 subgroup; those breast cancer patients can receive not only PARP inhibitors, but also tamoxifen or other drugs for positive ESR1 patients as therapeutic drugs." (PMID 40141415, 2025). "This “synthetic lethality” effect of PARP‐1 inhibition is effective in breast cancer with BRCA mutations, but not in breast cancer with wild‐type BRCA and is enlarged to cover cancer cells showing other HR protein deficiencies." (PMID 39778077, 2025). "In summary, we show that FGFRi restores PARP trapping and PARPi antitumor efficacy in PARPi-resistant breast cancer by decreasing HR through the PARP1 p-Y158/BRG1/MER11 axis, suggesting that PARP1 p-Y158 is a biomarker for PARPi resistance that can be overcome by combining FGFRis with PARPis." (PMID 40460005, 2025). "In docetaxel-resistant breast cancer tissues, the expression of PRMT1 and PARP1 was increased." (PMID 40927753, 2025). "Additionally, genes with CNV amplification, such as PARP1 and TOMM20, were also found to be upregulated in breast cancer, while genes with CNV deletion, such as PTEN, were downregulated." (PMID 40564403, 2025). "Parthanatos, a novel form of programmed cell death mediated by PARP1 and driven by DNA damage, has not been comprehensively characterized in breast cancer (BC)." (PMID 40564403, 2025). "This may imply that PARPis targeting both DNA-damage-responsive PARPs (PARP1 and 2) and PARP14 may possess increased antitumor potential in breast cancer." (PMID 38612413, 2024). "The Hoosier Oncology BRE09-146 phase 2 trial also demonstrated that adding another PARP1 inhibitor rucaparib to cisplatin did not improve the 2-year DFS benefits in TNBC or gBRCA1/2 m breast cancer with residual disease post-neoadjuvant therapy." (PMID 39334297, 2024). "Therefore, PARP1 > 6, p50 > 2, and TNF-α > 4 had a good predictive effect on postoperative metastasis of breast cancer." (PMID 38388665, 2024). "Theoretically, reduced PARP1 expression decreases PARPi sensitivity by reducing PARPi binding sites, as has been shown in the PDX model of breast cancer, and in vitro studies in human ovarian cancer tumor lines have shown that PARP1 deficiency leads to PARPi acquired resistance." (PMID 39318358, 2024). "To confirm the relationship between PARP1 and CDK4/6i resistance over a wider range, we obtained the IC50 for the CDK4/6i palbociclib in 30 breast cancer cell lines from the GDSC database and paired them with corresponding PARP1 mRNA level data gained from CCLE." (PMID 38037159, 2023). "Hence, although the PRMT6 and PARP1 inhibitors exhibit unique effects, targeting PARP1 and PRMT6 exerts synergetic effects on breast cancer progression by targeting the circadian rhythm." (PMID 36941223, 2023). "Furthermore, PARP1‐inhibition via Olaparib resulted in the dissolution of the PRMT6/PARP1/CRL4B complex, and strengthening the circadian rhythm amplitude and inhibiting breast cancer progression." (PMID 36941223, 2023). "The poly(ADP-ribose) polymerase 1 (PARP1) inhibitor olaparib was not effective against ALDH+ breast cancer cells because of increased PARP1 expression." (PMID 37686694, 2023). "What is also interesting, they found that not all expressed chemokines in studied breast cancer cell line are regulated by PARP1." (PMID 35585513, 2022).
breast cancer (continued). "As a substrate of PARP1/2, [18F]SuPAR was developed to image PARP1/2 activity and its uptake was significant reduced in an orthotopic breast cancer model rather than in a subcutaneous model." (PMID 36438061, 2022). "This is inconsistent with a recent study that showed that olaparib increased breast cancer bone metastasis via PARP2 but not PARP1 using myeloid cells." (PMID 35269669, 2022). "Cooperation of MET inhibitors with PARPi has been reported in breast cancer cell lines exposed to hypoxia that resulted in MET activation and nuclear transport where it could phosphorylate PARP1 directly." (PMID 35628590, 2022). "As such, there is significant interest in refining the selectivity and potency of PARP-1 inhibitors such as NMS-P118, a selective compound that inhibits PARP-1 80-fold more potently than PARP-2 and totally represses the growth of breast cancer cells and pancreatic ductal adenocarcinoma xenografts." (PMID 35158955, 2022). "High PARP-1 expression was correlated with poor prognosis in lymph node negative early breast cancer." (PMID 33572586, 2021). "Further, CHD4 depletion could increase sensitivity to trastuzumab treatment of HER2+ breast cancer cells, and CHD4 silencing improves sensitivity to cisplatin and PARP1 inhibitor in TNBC cells." (PMID 33981601, 2021). "Olaparib is a PARP1 and PARP2 dual inhibitor recently FDA approved for advanced breast cancer treatment; its effects on bone metastasis are unknown." (PMID 32443642, 2020). "Here, we investigated the effects of nutlin-3a on PARP1 in MCF-7, a human breast cancer cell line." (PMID 32405340, 2020). "Surprisingly, the expression of KLF4 was significantly correlated with the expression of PARP1 and vice versa in breast cancer tissues, which indicates that KLF4 and PARP1 are co‐accumulated in most breast cancer tissue including TNBC, HER2‐positive, and ER/PR‐positive breast cancer." (PMID 33231937, 2020). "PARylated PARP-1 is accompanied by obvious upregulation of HMGB1 and LC3II in breast cancer cells." (PMID 33158052, 2020). "Presently, PARP-1 inhibition is mainly utilized in the treatment of triple-negative breast cancers (TNBCs), but not in the treatment of ER+ breast cancers." (PMID 32059481, 2020). "Co‐localizations of both PARP1 and PAR with KLF4 were measured in breast cancer tissue specimens." (PMID 33231937, 2020). "Therefore, our findings demonstrate a potential novel therapeutic strategy to target BRCA‐proficient TNBC breast cancer by exploiting the synergism of KLF4 and PARP1." (PMID 33231937, 2020). "Remarkably, NGB treatment lowers oxidative stress upon H2O2 (400 μM; 30 min) stimulation, and PARP-1 cleavage under DTX treatment (100 nM; 48 h) in all breast cancer cell lines considered, although significant effects were observed at higher globin concentrations than in MCF-7 cell lines." (PMID 32872414, 2020). "Since we observed that P65 and PARP1 interact in breast cancer cells, we wanted to examine whether it is bound at the CCL2 promoter and if the binding is affected due to PARP1 inhibition." (PMID 32455851, 2020). "So we combined PARP1, XRCC4 and ERCC1 to detect the prognosis of breast cancer." (PMID 33184404, 2020). "In addition, anti-cancer therapy which combine PARP inhibition and genotoxic chemotherapeutic agents according to the expression of PARP1, γH2AX, BRCA1, and BRCA2 has been suggested for breast carcinomas and Ewing sarcomas." (PMID 29784019, 2018). "Moreover, the expression pattern of PARP1, γH2AX, and BRCA1/2 predicted shorter survival of various human malignant tumors including breast carcinoma and soft tissue sarcomas." (PMID 29784019, 2018).
breast cancer (continued). "Furthermore, ternary complex formation and PARP1 redistribution protect cells from DNA damage by promoting DNA repair, and support growth of BRCA1-null mammary tumors, which are sensitive to PARP inhibitors." (PMID 29158484, 2017). "However, relatively little is known about the regulatory mechanism of PARP1 expression and the determinants of PARP inhibitor sensitivity in breast cancer cells." (PMID 29212245, 2017). "In summary, NHERF1 expression could be considered a new potential biomarker in combination with PARP1 and BRCA1 expression to stratify breast cancer patients." (PMID 29029467, 2017). "Furthermore, stable expression of Flag-RNF144A in human breast cancer MCF-7, MDA-MB-231, and SK-BR-3 cells resulted in a decrease in the protein levels of endogenous PARP1." (PMID 29212245, 2017). "Moreover, our previous study demonstrated that the combined expression pattern of PARP1, γH2AX, BRCA1, and BRCA2 is very helpful in the prediction of the prognosis of breast carcinoma." (PMID 27643881, 2016). "Similarly, we previously reported on the prognostic significance of the combined expression patterns of the DDR molecules PARP1, γH2AX, BRCA1, and BRCA2 designated as CSbbph (combined score for the BRCA1, BRCA2, PARP1, and γH2AX) in breast carcinoma." (PMID 27643881, 2016). "Immunohistochemistry was used to examine the expression of PARP1 and BRCA1/BRCA2 in breast cancer." (PMID 25865228, 2015). "In addition, higher frequency (P < 0.01) of autoantibodies to PARP1 and BRCA2 was found only in breast cancer sera." (PMID 25865228, 2015). "A high level of PARP1 expression was shownto correlate with a more aggressive phenotype of breast cancers (BCs)(estrogen-negative BC)." (PMID 26483957, 2015). "Interestingly, PARP-1 is highly expressed in a variety of cancers, including breast and hepatocellular carcinoma (HCC), and is correlated with poor prognosis in early breast cancers." (PMID 24202328, 2013). "None of these studies considered PARP-1 activity together with BRCA1 functional status, except in the case of BRCA1-mutated cancers, which represent only around 5% of all breast cancers." (PMID 24191908, 2013). "Molecule like XAV939 can be used to target cancers harboring BRCA (such as breast cancer) and/or dysregulated Wnt-β-catenin signaling (such as colorectal cancer) without affecting PARP-1." (PMID 21504625, 2011). "Several PARP1 inhibitors are at different stages of clinical development, olaparib (previously known as AZD2281) has been evaluated in a phase 1 study where 60 patients with breast cancer were enrolled, of these, nine patients had an objective response." (PMID 20979652, 2010). "Therefore, we combined PARP1, p50 and TNF-α to detect breast cancer prognosis." (PMID 38388665, 2024). "Indeed, while colon cancer cells underwent apoptosis, as shown by DNA fragmentation, caspase-3 activation, and PARP1 degradation, breast cancer cells seemed to not undergo apoptosis." (PMID 39334877, 2024). "Some new substrates of USP1 have also been found in several tumors, such as karyopherin subunit alpha 2 and ERa in breast cancer, ID2 in gastric cancer, c-kit and TBLR1 in liver cancer, TAZ in osteosarcoma and hepatocellular carcinoma, Snail in ovarian cancer, and PARP1 in cholangiocarcinoma." (PMID 39513905, 2024). "This study only preliminarily discussed the predictive role of the DNA repair genes PARP1 and NF-κB pathway proteins on postoperative breast cancer metastasis but has not yet further studied their regulatory mechanisms in breast cancer metastasis and the screening of drug targets." (PMID 38388665, 2024). "Besides, our Circ-21 caused cell cycle arrest in G2/M phase induced by PARP-1 activation, and in addition, VEGF decreased, which reduces the malignancy of the breast cancer cells by not forming new blood vessels to nourish the tumor." (PMID 36499129, 2022).